NOTCH1 (notch receptor 1)
Diseases named in the same sentence as NOTCH1 in open-access papers (continued):
Sharing a sentence is not in itself a finding about the gene and the disease.
tumor (continued). "To further explore the related mechanism, we conducted gene expression analysis of Notch1-driven TNBC tumours compared with non-Notch1-driven TNBC tumours." (PMID 32591500, 2020). "Because the therapeutic targeting of NOTCH1 presents a dilemma to date, the successful abrogation of NOTCH1 oncogenic activity shown in this study indicates a possibility for future tumor treatment." (PMID 32792479, 2020). "There is accumulating evidence that suggests that Notch1 plays an important role in tumor progression." (PMID 35582224, 2020). "Further studies are needed to understand the potential implications for those tumours with over-expressed Notch1-IC." (PMID 31605148, 2020). "In colon cancer transplant mouse models, Dll4 and Jagged1 presence in tumor endothelial cells was found to activate Notch1 in neighboring tumor cells." (PMID 33198378, 2020). "As the cytokine microenvironment within the thymus critically regulates T-cell development and is perturbed by tumor conditioning, we assessed cytokines for their role(s) in reciprocally regulating Notch1 and Ikaros/IRF8 expression in arrested T cells." (PMID 32582141, 2020). "Experimental manipulation of NOTCH1 signaling in HNSCC cell lines harboring either mutant or wild-type NOTCH1 further supports a tumor suppressor function." (PMID 33322834, 2020). "Miao and colleagues (2020) have recently suggested that NOTCH1 activation can regulate the cell cycle and attenuate BRCA1 deficiency-induced G2/M blockade and genomic instability, thus providing tumor cells with a survival advantage." (PMID 33076453, 2020). "On the other side, among the eight upregulated miRNAs upon DBZ treatment, we expected to find putative tumor suppressor miRNAs that are usually downregulated in NOTCH1-induced T-ALLs." (PMID 32708470, 2020). "We validated these observations by confirming that the tumours with Notch1 mutations had a higher stromal CD45+ and CD3+ infiltrate than tumours that were wild type for Notch1." (PMID 33168804, 2020). "In conclusion, we demonstrate that ATRA exerts a significant anti-tumor action only in TNBC cells showing constitutive NOTCH1 activation." (PMID 33081033, 2020). "NOTCH1 showed high-intensity immunostaining with localised distribution in the nucleus and cytoplasm of tumour parenchyma cells." (PMID 32386517, 2020). "Overall, these data indicate that miR-22-3p overexpression significantly reduces tumor progression and increases overall survival in vivo, probably through its effects on NOTCH1 oncogenic targets." (PMID 32708470, 2020). "This tumour suppressor gene targets NOTCH1, being an important protein in cell proliferation control." (PMID 33024167, 2020). "In the present study, we demonstrate that ATRA exerts a significant anti-tumor action in TNBC cells characterized by constitutive NOTCH1 activation." (PMID 33081033, 2020). "In various tumor models, we have consistently observed that the Notch1 signaling pathway functions as a crucial molecular determinant in governing fibroblasts’ regulatory role in tumor progression and metastasis." (PMID 33109684, 2020). "Macrophages found in the tumor microenvironment participate in the regulation of vasculature remodeling, and strongly express Notch1, Notch2, and Notch4, together with VEGFR1." (PMID 30917608, 2019). "The higher relevance of Notch1 than of Notch2 to the tumor-stroma-inflammation networks in TNBC was corroborated by similar findings that were obtained with NOTCH1 vs. NOTCH2 co-expression analyses performed with IL-1β." (PMID 31105691, 2019). "The results showed that CD49f, ERα and NOTCH1 were significantly co-expressed in the primary tumor tissues." (PMID 31122254, 2019).
tumor (continued). "The longevity of Notch1-expressing tumour cells, along with their multipotency, establishes that Notch1 is expressed in vivo in CSC." (PMID 30696875, 2019). "Overall, this study suggests a mechanism whereby NICD mediated SERPINE1 downregulation via ETV7 contributes to several of the tumour-suppressive features of NOTCH1 signaling." (PMID 31827722, 2019). "Combining lineage tracing in two tumour models with transcriptomic analyses, we found that Notch1+ tumour cells are undifferentiated, proliferative and capable of indefinite self-renewal and of generating a heterogeneous clonal progeny." (PMID 30696875, 2019). "In this study, our observation proved that curcumin-PDT can block Notch signaling pathway and tune down the expression of key factors such as Notch-1 and NF-κB, thus inhibiting tumor growth." (PMID 31417656, 2019). "The presence of Notch1 in tumor tissue was significantly associated with TNBC subtype (P=0.041), high metastasis rate (P=0.035), tumor-node-metastasis (TNM) stages, and ALDH1 status, a known marker of cancer stem cells (CSCs)." (PMID 31379945, 2019). "DLL4 acting through Notch1/4 plays key roles such as regulating endothelial cells during normal and tumour angiogenesis." (PMID 31589383, 2019). "We propose a link between Notch1-induced expression of tumor-promoting genes and activation of processes contributing to a more aggressive MCL phenotype." (PMID 31676012, 2019). "In parallel, in the contact-dependent process, TNFα-driven activation of p65 - mainly in the tumor cells but also in the MSCs - has given rise to elevated Notch1 expression and activation." (PMID 31105691, 2019). "To test this possibility, we investigated Notch1/2 expression in peripheral bloods and tumor tissues, and then assessed the effect of Notch signaling inhibition on Tregs/Th17 cells function in GC patients." (PMID 30988066, 2019). "Accordingly, we showed that OMP-52M51 reverts the strong induction of gene signatures related to tumor cell migration and adhesion upon Notch1 activation and prevents DLL4-stimulated migratory capacity of MCL cells." (PMID 31676012, 2019). "The difference in Notch1 expression between the tumours from which SJG6 and SJG26 were derived was particularly striking." (PMID 31827722, 2019). "Together, these data show that the epithelial programs driven by NOTCH1 in KPN tumor cells rewire the TME and generate an immunosuppressive, pro-metastatic environment." (PMID 31526760, 2019). "In contrast, the tumor samples harboring PGRMC1 high-expression have reduced the genomic alterations rate of NOTCH1 genes." (PMID 31970154, 2019). "NOTCH1 gene alterations are more common than previously reported and reveals a role of NOTCH1 modifications in tumor metastasis." (PMID 31369215, 2019). "Consistently, we also found a tight correlation between the cells that express Notch1 in normal crypts and in tumours." (PMID 30696875, 2019). "The NOTCH1 pathway is also a direct target of the tumor suppressor miR-146a which, upon re-expression, can inhibit GBM development by reducing GSCs migration." (PMID 31450858, 2019). "By serving as a ceRNA for miR-34a, circ-ASH2L promoted tumor invasion, proliferation and angiogenesis by regulating miR-34a expression to active Notch 1 pathway." (PMID 31718694, 2019). "The resulting frequencies of some mutated genes such as NOTCH1 (33.3%), PIK3CA (25.6%), and KMT2D (30.8%) were higher compared to that in previously single-tumor studies." (PMID 30975989, 2019). "Notch1 has been found in a higher state of activation in tumor cells from colorectal cancer patients with lymphatic metastasis or distant metastasis than in those at an early stage, and these cells have a higher invasion and metastasis ability." (PMID 30622441, 2019).
tumor (continued). "High expression of Notch1, 2, and Jagged1 can be correlated with tumor progression of myeloma and it was proposed that Notch has an activating role of interleukin 6 (IL-6) proliferating signals in the bone marrow, enhancing tumor growth." (PMID 30917608, 2019). "To determine how epithelial NOTCH1 controls metastasis, we examined the transcriptome of tumor-derived KPN versus KP organoids." (PMID 31526760, 2019). "To molecularly characterise the tumour cells that express the Notch1+ receptor, we initially assessed the expression of selected genes in sorted cells by qRT-PCR." (PMID 30696875, 2019). "Our results suggest that the tumour suppressive role of NOTCH1 in OSCC is mediated, at least in part, by inhibition of SERPINE1 via ETV7." (PMID 31827722, 2019). "Our study shows that Notch1+ expression labels a previously uncharacterised and distinct population of undifferentiated and self-renewing tumour cells, which clonally expand during tumour growth and generate heterogeneous lineages." (PMID 30696875, 2019). "Further studies revealed that circ-ASH2L promoted tumor invasion, proliferation and angiogenesis by regulating miR-34a, thus regulate Notch 1 expression." (PMID 31718694, 2019). "Collectively, our findings confirmed that Notch1 promotes GICs invasion self-renewal and tumor growth through the AKT/mTOR pathway mediated by CXCL12/CXCR4 axis and thus provide evidence of a promising target for GBM management." (PMID 31382985, 2019). "NOTCH1 expression is decreased in bladder cancer and its activation reduces cellular proliferation, suggesting that it has a tumor-suppressive role." (PMID 31137841, 2019). "Notch1 and Notch2 have been identified as key Notch receptors for eliciting T-cell effector function, including anti-tumor responses." (PMID 30940183, 2019). "miR-34a and miR-34a-5p function as tumor-suppressive miRNAs, inhibiting cell proliferation, cell-cycle progression, and cell invasion by targeting Notch1, Notch2, c-Met, CDK6, and EGFR." (PMID 30832246, 2019). "We determined the protein level of the Notch pathway-related factors in tumor tissues and found that As2O3 reduced the protein levels of Dll4, Notch1, and Hes1 in vivo." (PMID 31093499, 2019). "Unexpectedly, while in normal crypts the Notch1 and Lgr5 transcripts are enriched within the same cells, Notch1+ tumour cells showed a reduction in Lgr5 expression compared to non-labelled cells." (PMID 30696875, 2019). "We have previously shown that the Notch1 receptor is expressed in Intestinal Stem Cells (ISCs); given the critical role played by Notch signalling in promoting intestinal tumourigenesis, we explored Notch1 expression in tumours." (PMID 30696875, 2019). "In a previous study, ameloblastoma was found to express Notch1 and its ligand Jagged1 in polyhedral tumor cells in the central region of the tumor nest." (PMID 31018488, 2019). "IHC results showed that the expressions of ERα, ERβ, EGFR and Notch1 in tumor tissues were higher than those in adjacent normal tissues." (PMID 31511014, 2019). "Our findings suggest that Notch1 plays a fundamental role in the cytological differentiation of epithelial and mesenchymal components and the acquisition of tumor-specific characters in these odontogenic tumors, but not in odontogenic myxoma." (PMID 31018488, 2019).
tumor (continued). "They found that Jagged 1 and Notch 1 expression decreased after HOTAIR knockdown, indicating that HOTAIR regulates tumor progression in Rb through the activation of the Notch 1 pathway." (PMID 31798638, 2019). "In T-ALL cells, where mutations in NOTCH1 are frequent and well characterized, DLL4 plays an important role as part of the tumor microenvironment contributing to early steps of T-ALL cell growth." (PMID 31676012, 2019). "Both pharmacological intervention and RNA interference were employed to investigate the role of Notch1 in GICs self-renewal, invasion and tumor growth in vitro or in vivo." (PMID 31382985, 2019). "In contrast, VPA and suberoylbishydroxamic acid (SBHA) effectively upregulate Notch1 activity and suppress neuroendocrine (NE) tumor markers, induced apoptosis, and cell cycle arrest in vitro and in vivo." (PMID 31357442, 2019). "Recent studies have reported that NOTCH1 is implicated in cancer development and progression in NSCLC and is involved in tumor initiation, growth, EMT, and metastasis." (PMID 31217907, 2019). "Notch-1 was negatively while Notch-2 was positively correlated with prognosis and therefore they play a completely different role in tumor formation and development." (PMID 31198409, 2019). "The HCCLM6-shNotch1 cells with stable knockdown of Notch1, as well as control cells, were implanted into nude mice to observe the metastasis of tumor cells in vivo." (PMID 31477177, 2019). "In FL, mutations in NOTCH1 and NOTCH2 are significantly associated with FL HT or the presence of DLBCL zones in the FL tumor." (PMID 30802265, 2019). "Based on our findings at the mRNA levels, it is possible that DLL1, whose expression was elevated in MSCs by TNFα and IL-1β stimulation (through a p65-mediated pathway, as analyzed for TNFα stimulation), is a partner of tumor cell-expressed Notch1." (PMID 31105691, 2019). "The location and nature of these alterations provide solid genetic evidence that NOTCH1 acts mainly as a tumor suppressor gene in HNSCCs." (PMID 31191362, 2019). "Lineage tracing showed that Notch1+ tumour cells rapidly generate clones of marked progeny, visible already 4 days after labelling, and that these clones enlarge over time." (PMID 30696875, 2019). "To investigate the influence of Notch1 expression on tumor growth in vivo, we performed experiments according to the schematic diagram." (PMID 31382985, 2019). "To map the fate of Notch1+ tumour cells and establish their self-renewal capacity in vivo, we examined tumour-bearing N1-Cre/R26mTmG/Apc mice at different time points after administration of tamoxifen, from 4 days up to 90 days." (PMID 30696875, 2019). "In vitro and in vivo studies have shown that the introduction of an antisense oligonucleotide to human NOTCH 1 into the HPV16-positive cervical cancer cell line Ca Ski can inhibit tumour cell growth and reduce the tumourigenicity of the NOTCH 1 receptor." (PMID 31205475, 2019). "This study indicated that ERs were likely to promote NSCLC progression by modulating the integrated membrane receptor signaling network composed of EGFR, Notch1 and GSK3β/β-Catenin pathways and then affecting tumor cell behaviors." (PMID 31511014, 2019). "These increased pro-tumor properties were associated with a substantially increased expression in Src/CD155/MIF expression and stemness markers such as Notch1 and β-catenin." (PMID 31036057, 2019).
tumor (continued). "Abnormally increased Notch-1 inhibits tumor cell apoptosis and promotes the development and metastasis of tumors." (PMID 31198409, 2019). "It is reported that in HCC70, SUM149, and MDA-MB-231 TNBC cell lines, the c-Jun N-terminal kinase (JNK) protein promotes CSC self-renewal and maintenance via transcription of Notch1, whose activation affects migration and invasion of tumor cells." (PMID 31379945, 2019). "Both Notch1 and Notch2 have been identified as key players in anti-tumor T-cell immunity including induction of tumor-specific cytotoxic T lymphocytes (CTL) and memory T-cells." (PMID 30940183, 2019). "Another study went on to delineate the role of NOTCH1 in inhibiting tumor progression in BC, whereby inhibition of NOTCH1 resulted in tumor regression and prevention of recurrence in ~67% of the tumors studied." (PMID 31178825, 2019). "Molecularly, the transcriptional signature of Notch1+ tumour cells highly correlates with ISCs, suggestive of their origin from normal crypt cells." (PMID 30696875, 2019). "Despite its critical role in T-ALL, NOTCH1-targeting therapies have failed so far to produce strong anti-tumor responses, largely due to difficulties in finding acceptable therapeutic windows for these agents." (PMID 31399482, 2019). "In further studies it will be interesting to identify the ligands that bind Notch1 in the tumor cells." (PMID 31105691, 2019). "As2O3 disturbed the morphological development of tumor vessels and downregulated the protein levels of delta-like canonical Notch ligand 4 (Dll4), Notch1, and Hes1 in vivo." (PMID 31093499, 2019). "Overall, tumor:stroma interactions set the stage for Notch1 activation by pro-inflammatory signals, leading to CXCL8 induction and consequently to pro-metastatic activities." (PMID 31105691, 2019). "Of relevance, our results define a cellular hierarchy within tumours, whereby Notch1+ CSCs appear to be giving rise to Lgr5+ tumour cells." (PMID 30696875, 2019). "This pathway, which has both oncogenic and tumor-suppressive effects depending on the tissue and cellular context, includes four receptors, NOTCH1-4, and five ligands and regulates the transcription of multiple target genes." (PMID 31137841, 2019). "Sequencing identified germline and tumor amplified, expressed, high-impact druggable variants in two genes (ABL1, NOTCH1) and expressed, medium impact variants in three additional genes (MDM4, PAK4, MAP4K5)." (PMID 31208434, 2019). "In the mesenchymal component of ameloblastic fibroma, a strong immunohistochemical positivity of Notch1 is observed in the tumor cells forming the dental papilla-like tissue." (PMID 31018488, 2019). "We explored the roles of MSI2 and Notch1 signaling in CD44v6+ LCSCs by sphere formation assay, transwell assay, clone formation assay in vitro, and xenograft tumor models in vivo." (PMID 31888685, 2019). "In vivo, E2 promoted tumor formation and metastasis, which was inhibited by tamoxifen in a NOTCH1-dependent manner." (PMID 31122254, 2019). "In those lines for which the original tumour was available, there was a positive correlation between NOTCH1 mRNA expression and the mean intensity of nuclear Notch1 protein labelling in the corresponding tumour samples (R = 0.9241, p = 0.025)." (PMID 31827722, 2019). "This study unravels the tumor suppressive role of miR-92a involving EP4/Notch 1 signaling regulated by NF-κB in gastric cancer." (PMID 29849934, 2018).